PCDHGA12 (protocadherin gamma subfamily A, 12)
Description:
Potential calcium-dependent cell-adhesion protein. May be involved in the establishment and maintenance of specific neuronal connections in the brain.
Synonyms: PCDH-gamma-A12; CDH21; FIB3; KIAA0588
Tractability: Antibody: UniProt places it where antibodies can reach, with medium confidence; UniProt predicts a signal peptide or a membrane-spanning region; its Gene Ontology location is reachable by antibodies, with medium confidence.
Gene: Protein-coding gene on chromosome 5 (141,430,507 to 141,512,975, forward strand). Ensembl gene ENSG00000253159.
Subcellular location: Cell membrane
Subcellular location (Human Protein Atlas): Plasma membrane; Vesicles; Cytosol; Nucleoplasm
Gene Ontology:
Molecular function: cell adhesion molecule binding; calcium ion binding
Biological process: cell adhesion; homophilic cell-cell adhesion
Cellular component: plasma membrane; cell-cell junction; membrane
Genetic constraint (gnomAD): Loss-of-function variants: 43 observed, 63.21 expected, observed/expected ratio (o/e) 0.68, 90% interval 0.53 to 0.88. The upper end of that interval is the gene's LOEUF score, 0.88, which puts it in group 3 of 6, group 1 being the genes least tolerant of losing a copy. Missense variants: 1,236 observed, 1,301.6 expected, observed/expected ratio (o/e) 0.95, 90% interval 0.9 to 1. Synonymous variants: 520 observed, 579.6 expected, observed/expected ratio (o/e) 0.9, 90% interval 0.83 to 0.96.
Homologues: Orthologues: mouse Pcdhga12 (86% identical). Paralogues in human: PCDHGA10 (77% identical), PCDHGA11 (76% identical), PCDHGA4 (75% identical), PCDHGA7 (75% identical), PCDHGA6 (74% identical), PCDHGA3 (74% identical), PCDHGA1 (74% identical), PCDHGA5 (74% identical), PCDHGA8 (74% identical), PCDHGA9 (73% identical), PCDHGA2 (73% identical), PCDHGB5 (52% identical), and 49 more.
Diseases named in the same sentence as PCDHGA12 in open-access papers:
PCDHGA12 is named in the same sentence as 21 diseases in open-access papers, as found by Europe PMC text mining. Sharing a sentence is not in itself a finding about the gene and the disease. The quoted sentences say what the papers report.
lung carcinoma (2 papers, 2022 to 2024). "PCDHGA12, a member of the protocadherin gene family, has been recognized as a biomarker for lung cancer." (PMID 39649173, 2024).
PCDHGA12 also shares sentences with these, for which no sentence is quoted: psoriasis (2 papers); age-related macular degeneration (1); Alagille syndrome (1); breast carcinoma (1); cardiovascular disease (1); cervical cancer (1); Doyne honeycomb retinal dystrophy (1); endothelial dysfunction (1); essential hypertension (1); fibrosis (1); geographic atrophy (1); glioblastoma (1); infection (1); inherited disease (1); macular degeneration (1); Sorsby fundus dystrophy (1); Sotos syndrome (1); squamous cell carcinoma (1); tumor (1); Varicose veins (1).